HKDC1 (hexokinase domain containing 1)
Description:
Catalyzes the phosphorylation of hexose to hexose 6-phosphate, although at very low level compared to other hexokinases. Has low glucose phosphorylating activity compared to other hexokinases. Involved in glucose homeostasis and hepatic lipid accumulation. Required to maintain whole-body glucose homeostasis during pregnancy; however additional evidences are required to confirm this role (By similarity).
Synonyms: FLJ37767; FLJ22761; RP92
Tractability: Small molecule: it belongs to a druggable protein family. Antibody: UniProt places it where antibodies can reach, with high confidence. PROTAC: ubiquitination databases record sites on it; its protein half-life has been measured; a small molecule that binds it is known.
Target class: Enzyme; Transferase
Gene: Protein-coding gene on chromosome 10 (69,220,292 to 69,267,552, forward strand). Ensembl gene ENSG00000156510.
Subcellular location: Cytoplasm; Mitochondrion membrane; Photoreceptor inner segment
Subcellular location (Human Protein Atlas): Mitochondria
Pathways (Reactome):
Metabolism: Glycolysis
Gene Ontology:
Molecular function: glucokinase activity; hexokinase activity; ATP binding; D-glucose binding
Biological process: glucose 6-phosphate metabolic process; intracellular glucose homeostasis; glucose metabolic process; glycolytic process; carbohydrate derivative metabolic process; carbohydrate metabolic process; hexose metabolic process; organophosphate metabolic process
Cellular component: cytoplasm; mitochondrion; cytosol; photoreceptor inner segment; mitochondrial membrane
Genetic constraint (gnomAD): Loss-of-function variants: 61 observed, 93.83 expected, observed/expected ratio (o/e) 0.65, 90% interval 0.53 to 0.81. The upper end of that interval is the gene's LOEUF score, 0.81, which puts it in group 3 of 6, group 1 being the genes least tolerant of losing a copy. Missense variants: 1,201 observed, 1,251.5 expected, observed/expected ratio (o/e) 0.96, 90% interval 0.91 to 1.01. Synonymous variants: 465 observed, 495.09 expected, observed/expected ratio (o/e) 0.94, 90% interval 0.87 to 1.01.
Homologues: Orthologues: chimpanzee HKDC1 (99% identical), macaque HKDC1 (99% identical), rabbit HKDC1 (94% identical), pig HKDC1 (94% identical), guinea pig HKDC1 (93% identical), mouse Hkdc1 (91% identical), rat Hkdc1 (91% identical), dog HKDC1 (86% identical), zebrafish hkdc1 (75% identical). Paralogues in human: HK1 (71% identical), HK2 (68% identical), HK3 (53% identical), GCK (27% identical).
Diseases named in the same sentence as HKDC1 in open-access papers:
HKDC1 is named in the same sentence as 68 diseases in open-access papers, as found by Europe PMC text mining. Sharing a sentence is not in itself a finding about the gene and the disease. The quoted sentences say what the papers report.
liver cancer (18 papers, 2020 to 2025). An epithelial or non-epithelial malignant neoplasm that arises from the liver. "The aberrant expression of HKDC1 has been associated with patient survival outcomes, with its role in liver cancer progression involving upregulating the expression of PD-L1 through STAT1 activation in tumor cells." (PMID 40909948, 2025). "Aberrational expression of HKDC1 is associated with various cancers, including colorectal cancer, liver cancer, and breast cancer." (PMID 34044809, 2021). "The hub gene in our analysis ACSL5, ALDOA, and HKDC1 are directly associated with liver cancer." (PMID 38648205, 2024). "Its crucial interaction with mitochondria highlights HKDC1 as a promising therapeutic target in liver cancer treatment." (PMID 41049000, 2025). "Overall, this study provides a mechanistic basis for the application of HKDC1 as a potential therapeutic target in advanced liver cancer, and provides new ideas for the treatment of tumor patients." (PMID 40124623, 2025). "A recent report showed that the mitochondrial localisation of HKDC1 plays a crucial role in liver cancer progression by regulating ATP levels 27; however, the relationship between HKDC1 and ATP is currently unclear." (PMID 40520008, 2025). "Critically, HKDC1 sustains liver cancer progression via essential interactions with mitochondria; disruption of this interface induces mitochondrial dysfunction." (PMID 41049000, 2025). "In liver cancer, HKDC1 and atorvastatin have been identified as modulators of STAT1, influencing downstream PD-L1 expression and consequently affecting tumor progression." (PMID 40909948, 2025). "It has also been reported that HKDC1 is overexpressed in liver cancer tissues, and silencing HKDC1 can inhibit Wnt/β-catenin signaling and inhibit the proliferation and migration of liver cancer cells." (PMID 40124623, 2025). "HKDC1 inhibition in combination with anti-PD-1/PD-L1 enhances in vivo T cell antitumor response in liver cancer models in male mice." (PMID 38351096, 2024). "Recent studies indicate that HKDC1 has an oncogenic function in specific cancer types by different mechanisms, such as liver cancer, breast cancer, lymphoma, colorectal cancer, and lung cancer." (PMID 36518326, 2022). "When HKDC1 is ablated in liver cancer cells, mitochondrial dysfunction occurs which results in decrease ATP in the cells." (PMID 35902556, 2022). "Baicalin suppressed type 2 diabetes and liver cancer development by reduction in the m6A level of HKDC1 by repressing the levels of m6A-related gene, METTL3." (PMID 35955525, 2022). "Hexokinase domain component 1 (HKDC1) plays an oncogenic role in certain types of cancer, such as lymphoma, liver cancer, and breast cancer." (PMID 32943998, 2020). "High expression of HKDC1 is closely related to poor prognosis of liver cancer patients." (PMID 40124623, 2025). "Consequently, the strategic inhibition of HKDC1 and the administration of anti-PD-L1 therapies are anticipated to enhance therapeutic efficacy in treating liver cancer." (PMID 40909948, 2025). "Additionally, the novel hexokinase called hexokinase domain containing 1 (HKDC1) has been identified as playing a role in liver cancer progression, with increased expression in MASLD and HCC." (PMID 38921460, 2024). "Furthermore, when exposed to high glucose concentrations, baicalin controlled the N6-adenosine-methyltransferase (METTL3)/hexokinase domain containing 1 (HKDC1)/JAK2/STAT1/caspase-3 pathway in liver cancer cells." (PMID 38004113, 2023). "m6A of HKDC1 facilitated rapid development of liver cancer induced by type 2 diabetes." (PMID 35955525, 2022). "Moreover, the role of HKDC1 as an oncogene in liver cancer and colorectal cancer prompted us to investigate its functional effect in LUAD." (PMID 32943998, 2020). "In addition, others have reported increased levels of HKDC1 in liver cancer, among other cancers." (PMID 37198225, 2023).
liver cancer (continued). "In addition, increasing evidence shows that HKDC1 may play oncogenic roles in cancers, such as lymphoma, liver cancer, breast cancer and colorectal cancer, indicating that HKDC1 may serve as a therapeutic target in cancers." (PMID 32943998, 2020). "To determine if ZMAT3 inhibits HKDC1 expression in multiple cell lines, we performed RT-qPCR after ZMAT3 knockdown in SW1222 (CRC cells), HCEC-1CT (immortalized human colonic epithelial cells), and HepG2 (liver cancer cells)." (PMID 40391325, 2025).
gastric cancer (8 papers, 2022 to 2026). A primary or metastatic malignant neoplasm involving the stomach. "High HKDC1 levels were associated with poor prognosis in gastric cancer patients, correlating with enhanced invasion, migration, and resistance to cisplatin in vitro and in vivo." (PMID 39090094, 2024). "According to the findings of the current research, HKDC1 is associated with both the process of proliferation and glycolysis in gastric cancer." (PMID 37153834, 2023). "In this study, the use of bioinformatics allowed for the identification of hexokinase domain component 1 (HKDC1) as a gene linked to gastric cancer, which was found to be closely associated with glycolysis." (PMID 37153834, 2023). "Additionally, HKDC1 enhances diagnostic specificity in gastric cancer by discriminating malignant tissue and augmenting existing diagnostic modalities." (PMID 41049000, 2025). "In gastric cancer, HKDC1 silencing markedly reduces cellular proliferation and glycolysis, highlighting the essential role of HKDC1 in maintaining the proliferative capacity of these cells 22-25." (PMID 41049000, 2025). "HKDC1 is identified as a crucial protein involved in cancer metabolism, particularly in lung, liver, colorectal, and gastric cancers." (PMID 41049000, 2025). "HKDC1 is remarkably expressed in Gastric Cancer (GC) tissues and is related to shorter survival rates, suggesting a potential association with tumor progression." (PMID 41049000, 2025). "By reprogramming glycolytic and lipid metabolic pathways, HKDC1 enhances invasiveness and chemoresistance., for example, in gastric cancer, where it drives cisplatin resistance alongside glycolysis up-regulation." (PMID 41049000, 2025). "The RNA-binding protein hexokinase domain component 1 (HKDC1) is overexpressed in gastric cancer and plays a significant role in the disease’s progression and chemoresistance." (PMID 39090094, 2024). "Our findings indicate that glycolytic activity is hindered in gastric cancer cells when HKDC1 expression is reduced due to downregulation." (PMID 37153834, 2023). "It was shown that hexokinase domain containing protein-1 (HKDC1) is essential for gastric cancer cell glycolysis, carcinogenesis and EMT by activating the NF-κB pathway, resulting in resistance to 5-FU, oxaliplatin and cisplatin in gastric cancer patients." (PMID 37569598, 2023). "In order to investigate the role that HKDC1 plays in the progression of gastric cancer, AGS and MKN-45 cells were transfected with two different shRNAs directed against HKDC1." (PMID 37153834, 2023). "Taken as a whole, the inhibition of cell proliferation and glycolysis brought about by the downregulation of HKDC1 provided a potential new avenue for the investigation of gastric cancer as a research target." (PMID 37153834, 2023). "In gastric cancer, HKDC1 promotes EMT, further enabling metastatic dissemination." (PMID 41049000, 2025). "As a result, HKDC1 may serve as a potential research target for the detection and treatment of gastric cancer, an area that calls for additional investigation." (PMID 37153834, 2023). "As an oncogene in gastric cancer development, HKDC1 influences cell proliferation and glycolysis." (PMID 37153834, 2023). "The initial indication that HKDC1 is a tumorigenic gene in gastric cancer comes from these studies." (PMID 37153834, 2023). "Furthermore, due to its distinctive properties, HKDC1 is ideally suited to serve as a therapeutic target for gastric cancer." (PMID 37153834, 2023). "In addition, the downregulation of HKDC1 in gastric cancer cells resulted in a significant reduction in glucose uptake, lactate production, ATP synthesis, and ECAR, as well as an increase in OCR and modest inhibition of glycolysis." (PMID 37153834, 2023). "These preliminary data suggest that the gene HKDC1 plays an oncogenic role in gastric cancer." (PMID 37153834, 2023).
gastric cancer (continued). "However, very little is known about the role that HKDC1 plays in the development of gastric cancer or the metabolic processes of tumors." (PMID 37153834, 2023). "In addition, the oncogenic effect of HKDC1 in hepatocellular and colorectal cancers served as a driving force behind our decision to investigate the functional importance of HKDC1 in gastric cancer." (PMID 37153834, 2023). "Our investigation into the role of HKDC1 in gastric cancer was highly exciting because no one had ever reported on its significance before." (PMID 37153834, 2023). "As a consequence of our research, we looked into whether or not HKDC1 had any effect on the glycolysis process in gastric cancer cells." (PMID 37153834, 2023).
colorectal cancer (7 papers, 2020 to 2026). A primary or metastatic malignant neoplasm that affects the colon or rectum. "Quantitative proteomics revealed HKDC1 as the most significantly upregulated protein in ZMAT3-depleted colorectal cancer cells." (PMID 41842937, 2026). "Using quantitative proteomics, we identified HKDC1 as the most significantly upregulated protein in ZMAT3-depleted colorectal cancer cells." (PMID 40391325, 2025). "HKDC1 (hexokinase domain containing 1) is recognized as an oncogene in various cancers, yet its role in colorectal cancer (CRC) remains unclear." (PMID 40209953, 2025). "In addition, there is accumulating evidence that HKDC1 may play an oncogenic function in cancers such as lymphoma, liver, breast, and colorectal cancers." (PMID 37153834, 2023). "We chose to focus on HKDC1 because by quantitative proteomics, HKDC1 was the most strongly up-regulated protein in ZMAT3-depleted colorectal cancer (CRC) cells." (PMID 40391325, 2025).
hepatocellular carcinoma (7 papers, 2023 to 2026). A malignant tumor that arises from hepatocytes. "Here the authors report that HKDC1 expression is associated with hepatocellular carcinoma progression and PD-L1 mediated immune evasion." (PMID 38351096, 2024). "In conclusion, the accumulating evidence of HKDC1's association with immune cell infiltration and tumor size further underscores its role in overall survival and personalized therapeutic strategies in conditions like pancreatic adenocarcinoma and hepatocellular carcinoma." (PMID 41049000, 2025). "In this study, we identified Hexokinase Domain-Containing Protein 1 (HKDC1) as a crucial effector that links HCV infection to glycolytic reprogramming in hepatoma cells." (PMID 42043212, 2026). "Hepatocellular carcinoma progression involves HKDC1-mediated TCA cycle modulation 16, and pancreatic cancer studies confirm reduced glucose consumption and lactate output following HKDC1 knockdown in SW1990 cells." (PMID 41049000, 2025). "Hepatocellular carcinoma studies demonstrate that aberrant HKDC1 expression promotes immune evasion by inducing CD8+ T-cell exhaustion and facilitating PD-L1-mediated immunosuppression." (PMID 41049000, 2025). "Hepatocellular carcinoma studies establish significant correlations between HKDC1 expression and tumor burden 16,17." (PMID 41049000, 2025). "Notably, HKDC1 promotes tumor immune evasion during immunotherapy in hepatocellular carcinoma patients, and blocking HKDC1 prevents disease progression in hepatic carcinoma, T cell lymphoma, and lung adenocarcinoma." (PMID 40110992, 2025). "HKDC1 is significantly overexpressed in hepatocellular carcinoma (HCC) compared to non-cancerous tissues and is associated with poor overall survival rates in patients." (PMID 41049000, 2025). "Some studies revealed the specific mechanism of hexokinase domain component 1 (HKDC1) and immune checkpoint PD-L1 expression in hepatocellular carcinoma (HCC)." (PMID 40124623, 2025). "Although HKDC1 has nominal expression in normal hepatocytes, it is significantly upregulated in hepatocellular carcinoma (HCC) cells, implying that it plays an essential role in HCC." (PMID 37109475, 2023). "Clinical sample analysis indicates a correlation among HKDC1 expression, STAT1 phosphorylation, and survival in patients with hepatocellular carcinoma treated with atezolizumab (anti-PD-L1)." (PMID 38351096, 2024). "HKDC1 exhibits marked overexpression both in hepatocellular carcinoma (HCC) 15 and cholangiocarcinoma (CCA) compared to non-neoplastic tissues 16, correlating with diminished overall survival (OS) in HCC patients." (PMID 41049000, 2025).
lung adenocarcinoma (7 papers, 2020 to 2025). A carcinoma that arises from the lung and is characterized by the presence of malignant glandular epithelial cells. "For example, HKDC1 has been implicated in tumorigenesis of lung adenocarcinoma through modulation of AMPK/mTOR signaling." (PMID 37082446, 2023). "For instance, a study showed that HKDC1 promotes tumorigenesis and glycolytic metabolism in lung adenocarcinoma by regulating the AMPK/mTOR signaling pathway, suggesting a direct link between HKDC1 expression and metabolic reprogramming of cancer cells." (PMID 41049000, 2025). "HKDC1 promotes tumorigenesis and glycolysis in lung adenocarcinoma (LUAD) by regulating the AMPK-mTOR pathway, and targeting HKDC1 can delay LUAD progression." (PMID 40692442, 2025). "Previous bioinformatics study revealed that HKDC1 was significantly upregulated in lung adenocarcinoma (LUAD)." (PMID 32943998, 2020). "In lung adenocarcinoma, HKDC1 may influence the AMPK/mTOR signaling pathway to enhance proliferation, migration, invasion, glycolysis, EMT, and tumorigenicity." (PMID 41049000, 2025). "HKDC1 demonstrates significant upregulation in lung adenocarcinoma, where it critically promotes oncogenic processes including cell proliferation, migration, invasion, epithelial-mesenchymal transition (EMT), and tumorigenicity while enhancing glycolysis through the AMPK/mTOR signaling pathway." (PMID 41049000, 2025). "Similarly, in lung adenocarcinoma, HKDC1 promotes the tumorigenesis and bolsters glycolytic flux via the AMPK/mTOR signaling pathway, thereby facilitating invasiveness." (PMID 41049000, 2025). "HKDC1 is highly expressed in lung adenocarcinoma (LUAD) and could serve as a prognostic predictor for LUAD patients." (PMID 32943998, 2020).